ITLN1 (intelectin 1)
Diseases named in the same sentence as ITLN1 in open-access papers (continued):
Sharing a sentence is not in itself a finding about the gene and the disease.
cancer (27 papers, 2012 to 2025). A tumor composed of atypical neoplastic, often pleomorphic cells that invade other tissues. "As we noted in our work on adipose tissue in upper gastrointestinal cancer, increased production of visceral adipose tissue ITLN1 is a feature of cancer-induced weight loss." (PMID 35186726, 2022). "Reduced glycolysis was also observed in vivo in cancer cells in mice intraperitoneally injected with ITLN1, but increased glycolysis was observed in the adjacent cancer-associated adipocytes." (PMID 32669559, 2020). "Animal models and in-vitro investigations might focus on determining the direction of the causal relationship between ITLN1 and cancer." (PMID 35186726, 2022). "Changes in circulating ITLN1 levels have been associated with several cancers." (PMID 35186726, 2022). "Future studies with larger cohort sizes should also investigate whether cancer-induced weight loss leads to increased circulating ITLN1." (PMID 35186726, 2022). "ITLN1 could be associated with cancer formation and progression." (PMID 35186726, 2022). "The Cancer Genome Atlas (TCGA) database showed a significant decrease in ITLN1 mRNA levels in the majority of cancer types." (PMID 41218553, 2025). "Using HepG2, Hep3B, and SK-Hep1 cells, the authors demonstrated that LF binds to cell-surface ITLN1 with high affinity, triggering endocytosis and initiating downstream anti-cancer programs." (PMID 41149627, 2025). "The expression of ITLN1 shows significant variability among patients with different types of cancer." (PMID 41218553, 2025). "Immunohistochemistry and western blot analysis were used to ascertain protein expression of ITLN-1 in cancer and para-carcinomatous tissue, and further to evaluate the correlation between ITLN-1 mRNA expression and surgical prognosis after liver resection." (PMID 38050235, 2023). "Immunohistochemical staining showed that ITLN-1 was highly expressed in adjacent tissues of the same patient, and was lowly expressed in cancer tissues." (PMID 38050235, 2023). "Although these are relevant observations, a meta-analysis with a reliable methodological approach is required to quantify ITLN1 levels in cancer patients and healthy participants." (PMID 35186726, 2022). "The interest in the role of ITLN in cancer has been driven by the observation that ITLN1 levels differ between healthy individuals and patients with various types of cancer." (PMID 35186726, 2022). "Future studies should aim to explore this relationship and to develop a better understanding of the role of ITLN1 in these types of cancer." (PMID 35186726, 2022). "The source of ITLN1 variability between different types of cancer should be one of the main areas explored by future studies." (PMID 35186726, 2022). "The direction of the difference in circulating ITLN1 between cancer patients and control groups depends on cancer type." (PMID 35186726, 2022). "Studies analyzing the relationship between ITLN and cancer are focused on ITLN1; the available literature on ITLN2 and cancer is limited." (PMID 35186726, 2022). "Our results showed that expression level of ITLN1 was downregulated in cancer compared with normal tissues based on TCGA dataset and experimental validation." (PMID 34217290, 2021). "Reduced glycolysis was observed in the cancer cells in vivo in mice given intraperitoneally injections of ITLN1, while increased glycolysis was observed in the adjacent cancer-associated adipocytes." (PMID 34631530, 2021). "ITLN1 was significantly increased in the VAT of the cancer groups (CC P = 0.0001, CWS P = 0.02) compared with VAT in the control group but was not different between the cancer groups (P = 0.5)." (PMID 32232960, 2020). "Larger patient studies will be required in the future to ascertain any true difference in circulating ITLN1 in cancer." (PMID 32232960, 2020). "Recent evidence shows the emerging roles of intelectin 1 (ITLN1), a secretory lectin, in human cancers." (PMID 25965823, 2015).
cancer (continued). "While CD295 and ITLN1 expression did not correlate with survival outcomes in our analysis, these genes are involved in key pathways linked to cancer metabolism, inflammation, and immune modulation." (PMID 41221514, 2025). "Moreover, analysis of the Cancer Cell Line Encyclopedia (CCLE) database indicated generally low ITLN1 expression in HCC cell line." (PMID 41218553, 2025). "And CS2 upregulated gene ITLN1 serve as tumor suppressor factor in various cancers." (PMID 38549156, 2024). "Previous research reported variable ITLN1 levels for cancer patients and healthy individuals." (PMID 38482202, 2024). "Moreover, future studies should aim to assess ITLN1 expression in cancer patients by measuring its concentration in the blood, cancer tissue, and subcutaneous and visceral adipose tissue." (PMID 35186726, 2022). "However, the levels of ITLN1 used in many of these studies were in the μg/ml range, whereas the normal physiological concentration of ITLN1, even in cancer or cell culture supernatant, was in the ng/ml range." (PMID 35186726, 2022). "Most of the studies analyzing the relationship between ITLN and cancer focus on ITLN1." (PMID 35186726, 2022). "Further work is required to identify whether ITLN1 has utility as a biomarker for cancer occurrence or re-occurrence." (PMID 35186726, 2022). "The available literature indicates that ITLN1 might have a role in cancer formation and development since ITLN1 level was highly variable but different from healthy controls when patients with various cancer types were examined." (PMID 35186726, 2022). "Overall, ITLN1 level was highly variable in cancer patients but different from healthy individuals." (PMID 35186726, 2022). "Though not much is known about it, ITLN1 is thought to be important in driving genomic instability and mutation and cancer-promoting inflammation." (PMID 33450975, 2021). "We found increased expression of Itln1 and Intelectin‐2 in particular suggesting these adipokines may play a role in adipose changes in response to cancer." (PMID 32232960, 2020). "Thus, intelectin-1 staining would be useful in the differential diagnosis of epithelioid-type MPMs from other cancers." (PMID 22768319, 2012). "In brief, epithelioid-type MPM could be distinguished from all tested cancers (n = 201) by double positive staining of intelectin-1 and calretinin at 88% of sensitivity and 100% of specificity." (PMID 22768319, 2012). "ITLN1 is a newly discovered adipokine whose function in cancer development remains unclear." (PMID 41218553, 2025). "The reason for the reduced expression of ITLN-1 in cancer is unknown." (PMID 38050235, 2023). "We found that, compared with normal tissues, the TIMP1 protein was expressed highly and significantly in cancer samples, while the ITLN1, TSPAN11, CPRC5B, and CXCL13 proteins were expressed poorly in cancer samples." (PMID 33579281, 2021). "Compared with the expression levels in normal samples, ITLN1, TSPAN11, CPRC5B, and CXCL13 showed significantly low expression levels in most cancer types, including COAD, while TIMP1 was expressed highly in most cancer types." (PMID 33579281, 2021). "Overall, these findings suggest that ITLN1 could locally potentiate PI3K/Akt signaling and glucose uptake in cancer cells to promote survival." (PMID 35186726, 2022). "We recently identified ITLN1 and ITLN2 mRNA as increased in the visceral adipose tissue of gastrointestinal cancer patients and found that local but not circulating ITLN1 protein demonstrated a relationship with cancer cachexia." (PMID 35186726, 2022). "In their review, Arjmand and colleagues found no overall relationship between circulating ITLN1 and cancer." (PMID 35186726, 2022). "Our microarray results confirmed that expression of ITLN1 was higher in VAT in cancer although not confined to CC patients." (PMID 32232960, 2020). "Intelectin-1 was not expressed in the other cancers, except in some mucus-producing adenocarcinomas." (PMID 22768319, 2012).
cancer (continued). "Intelectin-1 was not expressed significantly in these cancers, except for some mucus-producing adenocarcinomas (marked with an asterisk)." (PMID 22768319, 2012). "Other cancers, except mucus-producing adenocarcinomas, were not stained significantly with anti-intelectin-1." (PMID 22768319, 2012). "The mechanisms by which ITLN1 may lead to either positive or negative change in cancer also deserve research attention." (PMID 35186726, 2022). "Intelectin-1 was not expressed in other cancers, except in mucus-producing adenocarcinoma." (PMID 22768319, 2012). "Since ITLN1 is a secretory protein, we investigated whether circulating ITLN1 levels are lower in patients with HGSC than in women without cancer." (PMID 32669559, 2020).
infection (8 papers, 2010 to 2025). The state of being infected such as from the introduction of a foreign agent such as serum, vaccine, antigenic substance or organism. "Secondly, the biological functional validation of the proteomic data requires further investigation, such as exploring the regulatory mechanisms of key node molecules (e.g., GPX3 or ITLN1) in infection models using gene editing technologies." (PMID 41428679, 2025). "Changes in mesothelial cell gene expression of CCL5, TLR4, TNF, ZFP36, EDN1 and ITLN1 1 hour after infection with S. epidermidis." (PMID 28542390, 2017). "There were expression differences in Cd244, but not Itln1 or Ly9, over the course of infection between resistant C57BL/6 and susceptible A/J and BALB/c." (PMID 21085469, 2010). "ITLN1 is a cell surface phagocytotic receptor that recognizes specific bacterial cell wall components and the absence of ITLN1 has been suggested to alter immune responses to infection and facilitate inflammation." (PMID 22509262, 2012).
metabolic disease (5 papers, 2021 to 2025). A congenital disorder (due to inherited enzyme abnormality) or acquired (due to failure of a metabolically important organ) disorder resulting from an abnormal metabolic process. "Omentin-1 (also known as intelectin-1) is a novel adipokine associated with metabolic diseases." (PMID 41204367, 2025).
cardiovascular disease (4 papers, 2020 to 2025). "ITLN1 variants have been implicated in various chronic diseases, such as human kidney stone disease and cardiovascular disease." (PMID 38529304, 2024). "Omentin-1 is encoded by the gene intelectin-1 (ITLN1), and its expression in PVAT protects against cardiovascular disease by targeting the immune system to reduce pro-inflammatory mediators." (PMID 41155468, 2025). "For the first time, our results show a local effect of MRA intake on epicardial fat from patients with cardiovascular disease, specifically on fatty acid transporters and on the anti-inflammatory epithelial marker, ITLN-1." (PMID 35455943, 2022). "One of the anti-inflammatory adipokines mainly expressed and secreted by epicardial fat is the intelectin-1 (ITLN-1), named also omentin, that could counteract these inflammatory processes and reduce the cardiovascular disease risk." (PMID 35455943, 2022).
bacterial infection (2 papers, 2017 to 2022). "Several genes identified through our experimental approach have been linked to roles in host responses to bacterial infection (CCL5, ITLN1), immune modulation (ZFP36, NFKBIA) and damage (EDN1) during PD or during episodes of PD peritonitis." (PMID 28542390, 2017).
colorectal (2 papers, 2017 to 2024). "Moreover, our recent study indicated that loss of TMEM207, which is critical for the proper processing of intelectin-1 in the colon mucosa, leads to insufficient intelectin-1 production, thus participating in colorectal carcinogenesis." (PMID 28422056, 2017).
adenocarcinoma (1 paper, 2012). A common cancer characterized by the presence of malignant glandular cells. "Histopathologically, it would be easy to distinguish the mucus-producing adenocarcinoma, which expressed intelectin-1, from MPM on pleura." (PMID 22768319, 2012).
respiratory diseases (1 paper, 2020). "The top ten genes (Clca1, Chil4, Itln1, Tff1, Muc5ac, Clca3b, Chodl, Pla2g4c, Mmp10, and Stac2) with the highest fold change are involved in various inflammatory responses and respiratory diseases." (PMID 33066398, 2020).
ITLN1 also shares sentences with these, for which no sentence is quoted: glioma (9 papers); malignant pleural mesothelioma (4); type 2 diabetes (4); atherosclerosis (2); brain tumor (2); epithelioid mesotheliomas (2); gastric adenocarcinoma (2); metabolic syndrome (2); pleural mesothelioma (2); polycystic ovary syndrome (2); renal carcinoma (2); tuberculosis (2); amyotrophic lateral sclerosis (1); atopic dermatitis (1); biphasic synovial sarcoma (1); bladder cancer (1); celiac disease (1); cerebrovascular diseases (1); chronic obstructive pulmonary disease (1); ciliopathies (1); endometrial cancer (1); endothelial dysfunction (1); epithelioid hemangioendothelioma (1); gastric tumor (1); gestational diabetes (1); glioblastoma (1); Hepatic steatosis (1); Hypertension (1); infectious disease (1); lipid metabolism disorders (1).
A further 11 diseases each share a sentence with ITLN1 in 1 paper.